GSTA1 (glutathione S-transferase alpha 1)
Description:
Glutathione S-transferase that catalyzes the nucleophilic attack of the sulfur atom of glutathione on the electrophilic groups of a wide range of exogenous and endogenous compounds (Probable). Involved in the formation of glutathione conjugates of both prostaglandin A2 (PGA2) and prostaglandin J2 (PGJ2). It also catalyzes the isomerization of D5-androstene-3,17-dione (AD) into D4-androstene-3,17-dione and may therefore play an important role in hormone biosynthesis. Through its glutathione-dependent peroxidase activity toward the fatty acid hydroperoxide (13S)- hydroperoxy-(9Z,11E)-octadecadienoate/13-HPODE it is also involved in the metabolism of oxidized linoleic acid.
Synonyms: GST-epsilon; GST2; GSTA1-1; GTH1
Tractability: Small molecule: a structure with a bound ligand is known; a high-quality ligand is known; it has a high-quality binding pocket; it belongs to a druggable protein family. PROTAC: ubiquitination databases record sites on it; a small molecule that binds it is known.
Target class: Enzyme
Safety:
Unwanted effects reported when the protein is acted on. In parentheses: how it was acted on, where the effect was seen, and who reports it.
anemia (source: ClinPGx)
Gene: Protein-coding gene on chromosome 6 (52,791,371 to 52,803,881, reverse strand). Ensembl gene ENSG00000243955.
Subcellular location: Cytoplasm
Subcellular location (Human Protein Atlas): Cytosol
Pathways (Reactome):
Metabolism: Glutathione conjugation; Heme degradation
Cellular responses to stimuli: NFE2L2 regulating anti-oxidant/detoxification enzymes
Drug ADME: Azathioprine ADME
Gene Ontology:
Molecular function: fatty acid binding; glutathione peroxidase activity; glutathione transferase activity; molecular carrier activity; protein binding; steroid Delta-isomerase activity; phospholipid-hydroperoxide glutathione peroxidase activity
Biological process: epithelial cell differentiation; glutathione derivative biosynthetic process; glutathione metabolic process; linoleic acid metabolic process; prostaglandin metabolic process; heme catabolic process; xenobiotic metabolic process; cellular oxidant detoxification
Cellular component: cytosol; extracellular exosome; cytoplasm
Genetic constraint (gnomAD): Loss-of-function variants: 19 observed, 18.07 expected, observed/expected ratio (o/e) 1.05, 90% interval 0.73 to 1.54. The synonymous counts are far from expectation, so gnomAD's model fits this gene poorly and the ratio says little. Missense variants: 281 observed, 248.5 expected, observed/expected ratio (o/e) 1.13, 90% interval 1.02 to 1.25. Synonymous variants: 122 observed, 87.69 expected, observed/expected ratio (o/e) 1.39, 90% interval 1.2 to 1.62.
Homologues: Orthologues: chimpanzee GSTA1 (99% identical), rat Gsta3l1 (58% identical), zebrafish gstp1.1 (31% identical), tropical clawed frog gstp1 (29% identical), Caenorhabditis elegans gst-3 (27% identical), Caenorhabditis elegans gst-39 (27% identical), Caenorhabditis elegans gst-23 (27% identical), Caenorhabditis elegans gst-37 (27% identical), Caenorhabditis elegans gst-29 (26% identical), Caenorhabditis elegans gst-32 (26% identical), Caenorhabditis elegans gst-41 (26% identical), Caenorhabditis elegans W10C8.4 (25% identical), and 31 more. Paralogues in human: GSTA2 (95% identical), GSTA3 (91% identical), GSTA5 (90% identical), GSTA4 (53% identical), GSTP1 (30% identical), GSTM2 (27% identical), GSTM1 (25% identical), GSTM3 (24% identical), GSTM4 (24% identical), GSTM5 (23% identical), HPGDS (21% identical).
Diseases named in the same sentence as GSTA1 in open-access papers:
GSTA1 is named in the same sentence as 89 diseases in open-access papers, as found by Europe PMC text mining. Sharing a sentence is not in itself a finding about the gene and the disease. The quoted sentences say what the papers report.
breast carcinoma (12 papers, 2009 to 2025). "Decreased glutathione S-transferase A1 (GSTA1) expression is associated with increased breast cancer mainly among them current smokers and lower consumption of vegetables." (PMID 36896338, 2023). "We had previously reported that loss of GSTA1 is a major determinant of neutropenia among breast cancer patients receiving standard dose FAC (5-fluorouracil, doxorubicin, cyclophosphamide) chemotherapy." (PMID 31086207, 2019). "Along these lines, rs3957357T in GSTA1 was reported to be associated with a higher risk of developing several malignant diseases, such as colorectal, and breast cancer." (PMID 27936036, 2016). "We estimated the breast cancer risk associated with multiple polymorphisms in the GST gene (GSTA1, GSTM1, GSTP1, and GSTT1) and the interaction with PAH–DNA adducts and cigarette smoking." (PMID 19440493, 2009). "We found little statistical evidence that PAHs interacted with GSTT1, GSTM1, GSTP1, and GSTA1 polymorphisms to further increase breast cancer risk." (PMID 19440493, 2009). "CYP2A6 and GSTA1 are both involved in metabolic activation of several procarcinogens, and thus have been linked (in expression levels or genotypes) to the etiology of cancers such as tobacco-related lung cancer, colorectal cancer and breast cancer." (PMID 29177108, 2012). "It has been reported that functional variation of GSTA1 is involved in the development of radiation-induced fibrosis in patients with breast cancer." (PMID 36896338, 2023). "A total of 16 genes were identified to be related to radiotherapy response, and low expression of SVOPL, EDAR, GSTA1, and ABCA13 was associated with poor overall survival and progression-free survival in breast cancer cases." (PMID 36896338, 2023). "Many studies have shown the relationship between GSTA1 and cancer, including breast cancer, hepatocellular carcinoma, and colorectal cancer." (PMID 33521125, 2021). "Moreover, univariate cox analysis indicated that only four of them (SVOPL, EDAR, GSTA1, and ABCA13) were associated with the overall survival (OS) of breast cancer patients." (PMID 36896338, 2023). "It has been demonstrated by our group that the variant GSTA1*B/B genotype is associated with higher risk of breast cancer among smokers compared with nonsmokers with the A/A* genotype." (PMID 19440493, 2009). "In conclusion, we identified that SVOPL, EDAR, GSTA1, and ABCA13 are potential prognostic biomarkers of patients with breast cancer undergoing chemoradiotherapy." (PMID 36896338, 2023).
lung carcinoma (12 papers, 2007 to 2024). "Overexpression of GSTA1 can mediate lung cancer cells metastasis by promoting epithelial–mesenchymal transition (EMT)." (PMID 38111060, 2023). "Results indicated a significant downregulation of CX3CL1, MS4A15, and GSTA1 in lung cancer cells, while EPS8L3, G6PD, KRT6A, and S100P were notably upregulated, in line with the bioinformatics analysis findings." (PMID 37315289, 2023). "GSTA1 is an enzyme that promotes the binding of glutathione to target electrophilic compounds and promotes lung cancer cell invasion and adhesion." (PMID 36712848, 2022). "Specifically with regard to lung cancer, the downregulation of the expression of GSTA1 by curzerene correlates with an inhibition of tumor proliferation and migration." (PMID 35048517, 2022). "Decreased GSTA1 in A549 lung carcinoma affects epithelial–mesenchymal transition markers’ mRNA expression and decreases invasion ability." (PMID 34209254, 2021). "Downregulation of GSTA1 has been shown to suppress growth and apoptosis induction in lung cancer cells." (PMID 32405336, 2020). "In lung cancer, overexpression of GSTA1 plays a role in tumor promotion." (PMID 38167017, 2024). "For example, a recent in vitro study suggested that GSTA1 may facilitate nicotine-induced lung cancer metastasis." (PMID 31086207, 2019). "Few antimalarial drugs such as Quinine, Quinidine have been reported to exhibit inhibitory effect on GSTM1, GSTP1; however, none of them has been reported to inhibit GSTA1 specifically, which has been found overexpressed specially in lung cancer." (PMID 32405336, 2020). "Of these, the functions of GSTA1 and HAS1 in lung cancer have been reported, whereas the role of LGI2 in cancer remained unknown." (PMID 32209727, 2020). "Previous studies have shown that GSTA1 over-expression in cell lines with no detectable GSTA1 levels such as the human retinal pigment epithelial (RPE) cells and human lung cancer (H69) cells does not affect growth rate." (PMID 23251616, 2012). "GSTA1 was not detectable in lung tissue, however, GSTP1 increased significantly in lung tumors, indicating that GSTP1 may play a role in detoxification and maintenance of lung cancer cells." (PMID 26569310, 2015).
hepatocellular carcinoma (11 papers, 2016 to 2025). A malignant tumor that arises from hepatocytes. "In conclusion, our data suggest that the TT genotype of GSTA1 is associated with an increased risk of occurrence of hepatocellular carcinomas and that decreased expression of GSTA1 is a marker of advanced and highly aggressive hepatocellular carcinomas." (PMID 27936036, 2016). "More recently, it has been documented that GSTA1-1 negatively regulates the mTOR signaling pathway and the over-expression of the isoenzyme in hepatocellular carcinoma cells showed enhanced AMPK activity and subsequent inhibition of the mTOR pathway." (PMID 37189435, 2023). "Recent studies have found that GSTA1 can suppress hepatocellular carcinoma progression and overexpression of GSTA1 is correlated with a better prognosis for patients." (PMID 35936694, 2022). "They found that hepatocellular carcinoma patients with higher GSTA1 had better prognoses, and GSTA1 overexpression can impair liver cancer cell proliferation and metastasis." (PMID 33946704, 2021). "Furthermore, SFN also increased the transcription of UDP-glucuronosyl transferase (UGT) 1A1 as well as glutathione S-transferase A1 (GSTA1) in human hepatoma HepG2 and HT29 cells in a time- and dose-dependent manner." (PMID 31003534, 2019). "To explore how GSTA1 function is related to each GSTA1 haplotype, we estimated promoter activity by luciferase gene reporter using six haplotype constructs that were transiently transfected in human hepatoma (HEPG2) cells." (PMID 29207608, 2017). "Moreover, cancer patients with high expression of GSTA1-1 in their tumors had better prognoses, and the isoenzyme may serve a protective role against hepatocellular carcinoma by suppressing the AMPK/mTOR-signaling pathway." (PMID 37189435, 2023). "Therefore, we speculated that the decrease of GSTA1 in advanced hepatocellular carcinoma may be mainly related to ROS accumulation which proved to be able to accelerate the progression of HCC23." (PMID 31892975, 2020). "At the level of transcriptional and enzymatic regulation, glutathione S-transferase A1 (GSTA1) and β-catenin (CTNNB1) have been identified as key drivers of ferroptosis resistance, particularly in sorafenib-treated hepatocellular carcinoma." (PMID 41140341, 2025). "GSTA1 and GSTA2 have been previously identified as biomarkers of liver injury (including ethanol injury) and hepatocellular carcinoma respectively." (PMID 38335183, 2024).
acute graft versus host disease (4 papers, 2017 to 2024). A syndrome of immunologically mediated tissue damage that may occur following an allogeneic transplant, usually affecting the skin, liver, and GI tract. "GSTA1 diplotypes with slow metabolizing capacity were associated with higher incidence of sinusoidal obstruction syndrome, acute graft versus host disease and combined treatment-related toxicity (p<0.0005)." (PMID 29207608, 2017). "We could not demonstrate a correlation between GSTA1 polymorphisms and NRM, acute graft-versus-host disease (aGvHD) in this small cohort, but there is a trend of higher aGvHD incidence in GSTA1*B*B patients." (PMID 37085674, 2023). "Polymorphisms of GSTA1, GSTM1, and GSTP1 were reported as risk factors for SOS and acute GvHD, while GSTA1 and GSTM1 have been associated with combined TRTs." (PMID 34956984, 2021). "There was a trend for low treosulfan AUC(0–∞) to be associated with rejection (hazard ratio (HR) (95% confidence interval (CI)) = 0.08 (0, 1.37); P = 0.08); four covariates were significant by association with 1-year mortality (GSTA1, NQO1 polymorphisms, incidence of acute GVHD and hepatic SOS)." (PMID 37846495, 2024).
colorectal cancer (4 papers, 2012 to 2022). A primary or metastatic malignant neoplasm that affects the colon or rectum. "An epidemiological study demonstrated that decreased expression of GSTA1 is associated with an increased risk of colorectal cancer, especially in consumers of well-done red meat, since GSTA1 is involved in the detoxification pathway of food-born heterocyclic amines." (PMID 29177108, 2012).
liver cancer (4 papers, 2015 to 2025). An epithelial or non-epithelial malignant neoplasm that arises from the liver. "It was also very interesting that liver cancer cell lines with stronger metastasis ability had a lower GSTA1 abundance compared with other cells, which showed less metastatic potential." (PMID 31892975, 2020). "So, it is reasonable that LKB1 inhibits the metastasis of GSTA1 overexpressed liver cancer cells by downregulating the expression of MMP-9." (PMID 31892975, 2020). "In the second phase, we performed functional analysis by altering GSTA1 expression in liver cancer cells and performed cytology experiments to characterize its biological role in HCC progression and investigated the underlying mechanism." (PMID 31892975, 2020). "We found that high GSTA1 restrained liver cancer cell proliferation, migration and invasion in vitro." (PMID 31892975, 2020). "We found that GSTA1 overexpression could inhibit liver cancer cell proliferation and metastasis through regulating LKB1/AMPK/mTOR directly or indirectly." (PMID 31892975, 2020). "Liver cancer cells 97H and SNU449 (with a very low GSTA1) were chosen as experimental cells and were infected with the lentivirus vectors constitutively expressing GSTA1." (PMID 31892975, 2020). "And it was also very interesting that liver cancer cells with lower malignancy and weaker metastasis ability (including HepG2 and PLC-PRF5) had higher GSTA1 compared with other cells, which showed higher malignancy and strong metastasis ability." (PMID 31892975, 2020). "The migration and invasion abilities of liver cancer cells (97H and SNU449) were weakened in GSTA1 groups." (PMID 31892975, 2020). "Subsequently, lentiviral vector carrying GSTA1 gene was successfully constructed and maintained high expression in 97H and SNU449 liver cancer cells." (PMID 31892975, 2020).
prostate carcinoma (4 papers, 2016 to 2026). A carcinoma that arises from epithelial cells of the prostate gland. "This supports the hypothesis that GSTA1 could play a role in the development of prostate cancer." (PMID 39063019, 2024).
adenoma (3 papers, 2019 to 2022). A neoplasm arising from the epithelium. "In adenoma-normal, we found downregulation of GSTA1 and GSTA2, which encode members of the α class of gluathione-S-transferase enzymes." (PMID 31211760, 2019).
alcoholic liver damage (3 papers, 2022). "Glutathione detoxification enzymes including Gsta1, Gstm3, Gstm1, Gstp1, Gclm, and Gclc play important roles in protecting against alcoholic liver damage and diseases." (PMID 35565941, 2022). "Glutathione detoxification enzyme genes, including Gsta1, Gstm3, Gstm1, Gstp1, Gclm, and Gclc, play important roles in protecting against alcoholic liver damage and diseases." (PMID 36359319, 2022). "In addition, ginseng Huang jiu could improve alcoholic liver disease by regulating the GSTP1, HRAS, AKR1B1, GSTA1, Androgen receptor (AR), GSR, and LDHB genes through bioinformatics analysis." (PMID 36034901, 2022).
Cirrhosis (3 papers, 2022 to 2025). A chronic disorder of the liver in which liver tissue becomes scarred and is partially replaced by regenerative nodules and fibrotic tissue resulting in loss of liver function. "BA infants show a significant decrease in antioxidant genes, including glutathione S-transferase alpha 1 (GSTA 1) which is negatively correlated with BA incidence and cirrhosis." (PMID 39369162, 2024).
liver diseases (3 papers, 2018 to 2024). "Here, we have shown that GSTA1 binds directly to FABP1, and higher expression of GSTA1 causes degradation of FABP1, which can alleviate liver diseases." (PMID 38791126, 2024).
non-small cell lung carcinoma (3 papers, 2020). A group of at least three distinct histological types of lung cancer, including non-small cell squamous cell carcinoma, adenocarcinoma, and large cell carcinoma. "GSTA1 is highly expressed in many non-small-cell lung cancer cell lines and plays a crucial role in anti-cancer drug resistance." (PMID 32708388, 2020).
Obesity (3 papers, 2014 to 2024). Accumulation of substantial excess body fat. "Higher levels of the protein F7 (coagulation factor VII) have been linked to cardiovascular disease and obesity, while previous research indicates that proteins ACY1 (aminocyclase 1) and GSTA1 (glutathione S-transferase alpha 1) are positively associated with T2D." (PMID 38337712, 2024). "It is suggested that, although the increased expression of Gsta1 protects against oxidative stress, the down-regulation of Gsta1 during chronic inflammation, such as that related to obesity, may potentiate its cytotoxic effects." (PMID 24913135, 2014).
type 2 diabetes (3 papers, 2014 to 2024). "SNPs within the GSTA1 were associated with smoking-related type 2 diabetes in Japanese." (PMID 39541108, 2024). "Thus in Japanese, GSTA1*B allele is a potential risk factor for smoking-related type 2 diabetes and hypertension." (PMID 24423050, 2014). "Moreover, one drug targeting GSTA1 named Curcumin has been approved to treat type 2 diabetes." (PMID 38614964, 2024).
bladder cancer (2 papers, 2016 to 2023). "Previous studies have investigated the relationship between GSTA1, GSTM1, GSTP1, and GSTT1 polymorphisms and bladder cancer (BCa) susceptibility, respectively, but the results remain inconsistent." (PMID 27631264, 2016).
colon adenocarcinoma (2 papers, 2012 to 2014). "Human colonic adenocarcinoma (Caco-2) cells in culture undergo spontaneous differentiation into mature enterocytes in association with progressive increases in expression of glutathione S-transferase alpha-1 (GSTA1)." (PMID 23251616, 2012). "The isothiocyanate, sulforaphane and the flavonoid, epigenin increased gene expression of phase II detoxifying enzyme such as glutathione S-transferase (GSTA1) and UDP-glucuronosyltransferase (UGT1A1) in human colon adenocarcinoma." (PMID 24559113, 2014).
COVID-19 (2 papers, 2021 to 2025). A disease caused by infection with severe acute respiratory syndrome coronavirus 2. "The distribution of polymorphisms in cytosolic glutathione S-transferases GSTA1, GSTM1, GSTM3, GSTP1 (rs1695 and rs1138272), and GSTT1 were assessed in 207 COVID-19 patients and 252 matched healthy individuals, emphasizing their individual and cumulative effect in disease development and severity." (PMID 34988113, 2021).
diabetes (2 papers, 2014 to 2024). "In addition, proteomic studies have demonstrated that higher levels of GSTA1 are associated with an increased risk of diabetes." (PMID 39541108, 2024). "Multivariable adjusted (age, gender, current smoking status, presence of diabetes, and cholesterol level, Model 3) Cox regression analysis has shown the lack of association between GSTA1 polymorphism and overall mortality (HR = 1.15; 95% CI:0.64-2.07; p = 0.650)." (PMID 24423050, 2014).
Endotoxemia (2 papers, 2011). "Endotoxemia resulted in a cumulative GSTA1-1 excretion of 11.2 (6.2 to 13.0) μg compared with 5.1 (3.9 to 9.4) μg 12 hours after LPS administration in dipyridamole- and placebo-treated subjects, respectively." (PMID 22129171, 2011). "Both GSTA1-1 and GSTP1-1 levels, respectively, increased during experimental endotoxemia (n = 30, P < 0.0001)." (PMID 21211004, 2011).